INS (insulin)
Diseases named in the same sentence as INS in open-access papers (continued):
Sharing a sentence is not in itself a finding about the gene and the disease.
type 1 diabetes (continued). "The overall lack of association between chemokines and autonomic parameters may be attributed to the administration of insulin in type 1 diabetes, which is known to have anti-inflammatory effects, thereby possibly reducing the expression of chemokines." (PMID 32908447, 2020). "Father was diagnosed with Type 1 diabetes at 15 years of age that required insulin therapy." (PMID 32670997, 2020). "Therefore, the aim of the present study was to examine systolic and diastolic echocardiographic parameters in relation to insulin dose in young patients with type 1 diabetes." (PMID 33370380, 2020). "Choice of insulin delivery for type 1 diabetes can be difficult for many parents and children." (PMID 31900152, 2020). "Clinical diagnosis of type 1 diabetes is an event marking the late stages of the destructive autoimmune process, when the number of functional β cells falls below the threshold required for adequate insulin production." (PMID 31660582, 2020). "Indeed, in vitro and clinical data in patients suffering from type 1 diabetes have shown in large clusters less insulin-expressing cells both in normoxic and hypoxic conditions and the larger islets were significantly reduced in size under hypoxia." (PMID 32766229, 2020). "Therefore, the aim of the present study was to evaluate parameters of both systolic and diastolic function according to insulin dose in a well characterized cohort of patients with type 1 diabetes." (PMID 33370380, 2020). "Therapies involving insulin administration are indispensable for people with type 1 diabetes." (PMID 32467827, 2020). "Type 1 diabetes is a chronic condition of blood glucose metabolic disorder caused by lack of insulin secretion from pancreas cells." (PMID 32784178, 2020). "Second, we have no direct measures of insulin resistance to assert the association of this condition with lung dysfunction in type 1 diabetes." (PMID 32344939, 2020). "Related with type-1 diabetes, polypeptide-p has shown action similar to human insulin in the body and, therefore, may be used as plant-based insulin replacement in patients with type-1 diabetes." (PMID 32872226, 2020). "Insulin-dependent diabetes is a multifactorial disorder that could be theoretically cured by functional pancreatic islets and insulin-producing cell (IPC) implantation." (PMID 30760321, 2019). "The sex difference seen between affected parents diagnosed before and after the birth of the index child supports the hypothesis that maternal insulin treatment protects against type 1 diabetes." (PMID 31346657, 2019). "For people with type 1 diabetes, glucose control during exercise is challenging, as without the physiological response of insulin to exercise, deficiencies or exaggerations in other hormonal responses can occur." (PMID 31161377, 2019). "Type 1 diabetes is a complex chronic condition which requires lifelong treatment with insulin." (PMID 31604437, 2019). "Despite the dearth of scientific tools available in 1922, insulin’s discovery rapidly launched a life-saving therapy for what we now know to be type I diabetes, and continually enhanced insulin therapeutics are now effectively applied to both major forms of this increasingly prevalent disease." (PMID 30357355, 2019). "In humans, the destruction of the insulin-producing β-cells by an immune attack, as occurs in type 1 diabetes (T1D), is a life-threating problem that leads to serious health complications associated with chronic hyperglycemia and a lifelong need for daily exogenous insulin therapy." (PMID 31569489, 2019). "In women with type 1 diabetes, insulin requirements increase averagely by 70% during pregnancy." (PMID 31828161, 2019). "Interestingly, glucagon agonism (low-dose glucagon) is likely to be applied together with insulin in the dual pump systems development for type 1 diabetes therapy." (PMID 31284506, 2019).
type 1 diabetes (continued). "Based on our experimental results, we hypothesized that the serum ucOC concentrations were regulated by exogenous insulin in patients with type 1 diabetes." (PMID 31050684, 2019). "This research suggests late type 1 diabetes has similar characteristics to young-onset disease and, in contrast to type 1 diabetes defined by autoantibody status alone, continues to have a severe phenotype: 89% were treated with insulin within 1 year of diagnosis, and 11% developed ketoacidosis." (PMID 30969375, 2019). "Further, by delaying glucose absorption, sotagliflozin may reduce the need for ultra-fast insulin in type 1 diabetes." (PMID 30819210, 2019). "Circumstances when the systemic endogenous insulin response could be lower, include insulin insufficiency (e.g., type 1 diabetes), or high insulin sensitivity which reduces insulin requirement." (PMID 31127081, 2019). "Type 1 diabetes is a chronic condition in which the pancreas produces little to no insulin, and the primary cause of Type 1 diabetes is believed to be an auto-immune destruction of the β cells." (PMID 31073328, 2019). "The association of the daily insulin dose with a higher QoL has not been described in type 1 diabetes." (PMID 30889868, 2019). "In another study, urinary albumin excretion along with heart rate variability significantly improved in type 1 diabetic patients who received 6-month combination treatment of C-peptide and insulin, indicating that C-peptide and insulin improve renal and autonomic nerve function in type 1 diabetes." (PMID 30430334, 2019). "They suggested that setting recording insulin therapy and dosage in the app might help the patients with type 1 diabetes." (PMID 31464191, 2019). "For individuals with type 1 diabetes, whose islets have an impaired ability to secrete insulin owing to the autoimmune destruction of their beta cells, exogenous insulin is typically administered preceding mealtimes in anticipation of spikes in blood glucose levels." (PMID 30799185, 2019). "Therefore, in this study we obtained glucose levels as well as plasma insulin levels in children with type 1 diabetes to evaluate the efficacy of a model—based closed-loop algorithm compared to an open-loop administration." (PMID 30849076, 2019). "Type 1 diabetes is insulin-dependent and mostly caused by the damage of pancreatic β cells that lead to the lack of insulin." (PMID 31835878, 2019). "Type 1 Diabetes is a chronic disease requiring glucose monitoring and intensive insulin therapy." (PMID 30875898, 2019). "People with type 1 diabetes treated with insulin pumps may use an automatic bolus calculator that allows them to determine the insulin dose based on the amount of carbohydrates consumed in the meal and an individual insulin sensitivity." (PMID 30871141, 2019). "In summary, treatment with sotagliflozin in combination with insulin in subjects with type 1 diabetes, significantly decreased glycated hemoglobin level, insulin dosage, body weight and systolic blood pressure, and, more importantly, without increasing the occurrence of hypoglycemia." (PMID 30819210, 2019). "Insulin detemir reduces the risk of nocturnal (severe and non-severe) hypoglycaemia even in patients with type 1 diabetes and recurrent severe hypoglycaemia." (PMID 31337371, 2019). "In type 1 diabetes patients, oral administration of sodium metavanadate and vanadyl sulfate in doses of 50–125 mg/day during 2 to 4 weeks, improves fasting plasma glucose levels and daily insulin requirements in type 1 diabetic patients." (PMID 30350272, 2019). "A possible way of treating autoimmune (Type I) diabetes could be the restoration of insulin production via the transplantation of insulin producing pancreas cells." (PMID 31781097, 2019). "Studies of type 1 diabetes suggest that residual endogenous insulin secretion reflected by C-peptide concentrations may have favorable effects on protection against the microvascular complications." (PMID 30430334, 2019).
type 1 diabetes (continued). "Persons with type 1 diabetes require insulin for survival in their life's; insulin may additionally be given as a daily shot or consistently with an insulin pump." (PMID 31663031, 2019). "From a clinical point of view, our results may serve as a first hint on how individuals with type 1 diabetes can maintain euglycemia based on orally administered carbohydrates during ~1 h of moderate-intensity exercise with little bolus insulin on board." (PMID 31174360, 2019). "Type 1 diabetes (T1D) is a chronic, organ-specific autoimmune disease characterized by the progressive destruction of pancreatic beta cells, which ultimately results in lifelong dependence on exogenous insulin." (PMID 31816979, 2019). "Thus, autoreactive anti-insulin B cells play a particularly important role in the pathogenesis of type 1 diabetes." (PMID 31444529, 2019). "Most people with Type 1 diabetes have low levels of persistent endogenous insulin production." (PMID 30955221, 2019). "Insulin therapy is the most common treatment for type-1 diabetes." (PMID 31645652, 2019). "However, the continuous blood glucose lowering effect induced by exogenous (basal) insulin (=permanent glycolysis) circumvents lipolysis as a main cellular fuel in individuals with type 1 diabetes." (PMID 31174360, 2019). "Islet transplantation has the potential to cure type 1 diabetes, but current transplantation protocols are not optimal and there is extensive loss of islet β‐cell insulin secretory function during the immediate post‐transplantation period." (PMID 31066521, 2019). "In summary, short-acting insulin analogues were associated with fewer nocturnal and severe hypoglycemic events and better glucose control (slightly lower HbA1c and lower postprandial blood glucose levels) when compared with regular human insulin in subjects with type 1 diabetes." (PMID 30622653, 2019). "Thus can be used to assess insulin treatment self-management in children with type 1 diabetes and their parents as well as a tool for effective nursing care." (PMID 30905141, 2019). "This is exemplified by the findings of attenuated glucose production in response to exogenous glucagon after one week of low carbohydrate diet (LCD) compared to the response after a week of high carbohydrate diet (HCD) in patients with insulin pump-treated type 1 diabetes." (PMID 31284506, 2019). "Type 1 diabetes (T1D) is an organ-specific chronic autoimmune disease leading to immune-mediated destruction of insulin-secreting beta cells within the pancreatic islets, resulting in lifelong dependence on exogenous insulin." (PMID 31514368, 2019). "Type 1 diabetes patients are asked to monitor their home glucose readings as well, including their fasting and random blood glucose readings, which determine the need for insulin dose adjustments." (PMID 31781665, 2019). "In addition, LADA is linked with type 1 diabetes associated variants outside of the HLA region including PTPN22, INS, and SH2B3." (PMID 30971952, 2019). "Insulin was life-saving when administered to patients with what we now know to be type I diabetes." (PMID 30357355, 2019). "Intensive insulin therapy is considered to be the standard treatment for type 1 diabetes." (PMID 31159842, 2019). "Clinical diagnostic models integrating clinical features with biomarkers have high accuracy for identifying type 1 diabetes with rapid insulin requirement, and could assist clinicians and researchers in accurately identifying patients with type 1 diabetes." (PMID 31558459, 2019). "Despite improvements in hyperglycaemia, islet transplant recipients with longstanding type 1 diabetes that achieve insulin independence often ultimately require resumption of insulin; although this picture is complicated by functional effects of transplant medications on beta cell health." (PMID 30767048, 2019). "This may be due to the substantial increase in the serum adiponectin level in patients with type 1 diabetes treated by insulin therapy." (PMID 31050684, 2019).
type 1 diabetes (continued). "This is because the decision made on whether to commence insulin for a given probability of type 1 diabetes will vary enormously due to other factors." (PMID 31558459, 2019). "The fact that LADA patients have more insulin production than patients with type 1 diabetes at time of diagnosis indicates that other mechanisms besides autoimmune destruction of the beta-cells may play a role in the pathogenesis." (PMID 30971952, 2019). "In Type 1 Diabetes, the ability to produce insulin is lost, and insulin must be injected." (PMID 31696324, 2019). "This is the first study investigating the interaction between pre-exercise blood glucose levels and the amount of orally administered carbohydrates during moderate-intensity exercise, depending on the dose of basal insulin in individuals with type 1 diabetes running on multiple daily injections." (PMID 31174360, 2019). "However, SGLT2 inhibitors have been investigated as an adjunctive therapy to insulin for patients with type 1 diabetes in clinical trials." (PMID 31198610, 2019). "Interestingly this energetic mismatch is also demonstrated in type 1 diabetes, providing additional direct evidence for the role of insulin." (PMID 31039789, 2019). "The importance of a glucose-dependent regulated period during childhood becomes more evident when following Type 1 diabetes patients (insulin-dependent; juvenile diabetes) who experience hypo- or hyperglycemic states and show marked decline in brain function and cognitive tasks later in life." (PMID 31572169, 2019). "In addition to the cell reprogramming strategies highlighted above, other groups are working to restore insulin-producing β cells by immunomodulation approaches to suppress the autoimmune attack characteristic of type 1 diabetes." (PMID 31686269, 2019). "Even if time in glucose target is still the main objective of the treatment of children with type 1 diabetes, the demonstrated reduction of insulin levels may contribute as well to improve long-term outcome." (PMID 30849076, 2019). "Interestingly, however, in an experimental animal model of type 1 diabetes, the levels of methylated INS DNA in β-cells increased as a direct result of proinflammatory stressors." (PMID 31428654, 2019). "Type 1 diabetes (T1D) is an autoimmune disease, characterized by destruction of insulin-producing pancreatic islet β-cells that results in lifelong dependency on exogenous insulin." (PMID 30669674, 2019). "This is utterly known that if the beta cell is not functional genetically, hyper-glycaemia will occur linked with insulin resistant surely happen; this is especially true family suffering of type I diabetes mellitus and due to the familial tendency of insulin secretory defects." (PMID 31402976, 2019). "Its expression is unchanged in type-1 diabetes or in insulin-resistant OZR." (PMID 30689673, 2019). "Furthermore, as the present study only included a very small sample size, it will be necessary to confirm the findings in follow‐up studies with additional insulin‐triggered type 1 diabetes patients." (PMID 30970177, 2019). "The generation of insulin-producing cells (IPCs) from pluripotent stem cells could be a breakthrough treatment for type 1 diabetes." (PMID 31822724, 2019). "Among the autoantigens, insulin plays the most important role in the type 1 diabetes process." (PMID 30970177, 2019). "The main aim of type 1 diabetes treatment is to ensure the stability of plasma insulin levels." (PMID 30905141, 2019). "Given that the problem of weight gain with intensive insulin treatment is known, the option of adding drugs that might attenuate this to treatment regimens for type 1 diabetes has been investigated in a number of trials." (PMID 28501906, 2018).
type 1 diabetes (continued). "A U-shaped relationship was observed between mean reimbursed expenditure and age, which is likely to be related to insulin therapy for people with type 1 diabetes at a younger age due to progression of the disease over time and the development of complications, as well as other diseases." (PMID 28190188, 2018). "Thus, this study investigated potential of RA-3 to augment insulin signaling in the STZ-induced type 1 diabetic rats." (PMID 30285704, 2018). "Therefore, for this analysis, type 1 diabetes was defined as current insulin use and self-report of type 1 diabetes." (PMID 29596402, 2018). "Furthermore, we showed that injection of alloxan increased blood glucose in parallel to a decrease in the body weight and plasma insulin levels, indicating a clear type 1 diabetic state in A/J mice." (PMID 29849493, 2018). "Considering the Phase II and III trials together, on average, addition of SGLT inhibitors to insulin replacement in type 1 diabetes resulted in a 5–6 mmol/mol (0.4–0.5%) reduction in HbA1c, a 3–4 kg weight loss and a 10–15% reduction in total daily insulin dose." (PMID 30132030, 2018). "Thus, present study aimed to examine the predictors of lipohypertrophy with particular emphasis on insulin regimens and types of insulin in a large sample of type 1 diabetes patients with appropriate statistical analysis." (PMID 30425682, 2018). "Metformin improved diabetic control with reduced insulin dose requirement without weight loss in overweight adults with C-peptide-negative type 1 diabetes during 4 months’ therapy." (PMID 29338714, 2018). "Furthermore, HEK-ProINS-Tf was demonstrated as an extra-long acting insulin analogue with liver-specific insulin action in streptozotocin (STZ)-induced type 1 diabetic mice." (PMID 29373562, 2018). "Type 1 diabetes, an organ-specific autoimmune disease with a multifactorial aetiology, is characterised by the immune-mediated destruction of beta cells in pancreatic islets, resulting in insufficient insulin production." (PMID 29594371, 2018). "Concurrently, in several other studies, an alternative strategy has been adopted in which glucose-responsive insulin-secreting cells can be generated following transplantation of hESC/iPSC-derived pancreatic progenitor cells into ectopic sites in immunodeficient or type 1 diabetic mice." (PMID 30594258, 2018). "Islet transplantation is a treatment option that can help individuals with type 1 diabetes become insulin independent, but inefficient oxygen and nutrient delivery can hamper islet survival and engraftment due to the size of the islets and loss of the native microvasculature." (PMID 29971529, 2018). "Meeting the twin challenges of hyperglycaemia and hypoglycaemia in type 1 diabetes may require additional adjunct pharmacotherapies to complement insulin replacement." (PMID 30132030, 2018). "Repeated injection of insulin lispro into lipohypertrophic areas has been reported to result in increased variability between injections in certain pharmacokinetic and pharmacodynamic parameters in patients with type 1 diabetes." (PMID 30116732, 2018). "The only therapeutic option for type 1 diabetes is to replace insulin." (PMID 30013597, 2018). "We identified a similar phenotype when genetically defined type 1 diabetes was diagnosed in individuals aged 31–60 years: 89% of patients were treated with insulin within 1 year of diagnosis and about one in nine were admitted to hospital with documented diabetic ketoacidosis." (PMID 29199115, 2018). "Moreover, different insulin absorption rates within the same region have also been reported in people with type 1 diabetes." (PMID 30116732, 2018). "We found no significant heterogeneity between tumor expression of the proteins of interest between diabetes type 1 and type 2 insulin users, except for p-ER (type 1 vs. type 2: OR = 0.28; 95%CI:0.08–0.95; p = 0.04), but after adjustment for menopause and BMI this difference was non-significant." (PMID 29486734, 2018).